RNU7-167P (RNA, U7 small nuclear 167 pseudogene)
Gene: Small nuclear RNA gene on chromosome 22 (35,249,772 to 35,249,833, forward strand). Ensembl gene ENSG00000238584.
Homologues: Orthologues: chimpanzee U7 (100% identical). Paralogues in human: RNU7-35P (87% identical), RNU7-7P (87% identical), RNU7-113P (85% identical), RNU7-175P (85% identical), U7 (85% identical), RNU7-124P (84% identical), RNU7-137P (84% identical), RNU7-138P (84% identical), RNU7-143P (84% identical), RNU7-152P (84% identical), RNU7-19P (84% identical), RNU7-34P (84% identical), and 143 more.